MMP2 (matrix metallopeptidase 2)
Diseases named in the same sentence as MMP2 in open-access papers (continued):
Sharing a sentence is not in itself a finding about the gene and the disease.
pancreatic cancer (continued). "MMP-2 protein expression in pancreatic carcinoma specimens with distant and lymph node metastasis was significantly higher than that in specimens without metastasis, indicating that MMP-2 level is associated with pancreatic adenocarcinoma invasion, metastasis and prognosis." (PMID 25452809, 2015). "Pancreatic cancer cells require the activation of MMP-2 during invasion and migration." (PMID 24511528, 2014). "Overall, these results suggested that EPHA4 may promote the motility and invasion of pancreatic cancer cells via the upregulation of MMP-2 and Snail, as well as the downregulation of E-cadherin." (PMID 24932309, 2014). "This suggests that OCT4 may be implicated in the development of pancreatic cancer through AKT pathway-mediated PCNA and MMP-2 expression." (PMID 25017645, 2014). "MMP2 was previously reported to increase ability of cancer cells to migrate and determination of MMP2 activity in pancreatic juice was told to be useful in diagnosing pancreatic cancer." (PMID 23304126, 2012). "Targeting of Stat3 activation may prove to be a more effective approach to controlling invasion than merely targeting individual molecules, such as VEGF and MMP-2, possibly representing a novel approach to regulating pancreatic cancer invasion." (PMID 20482858, 2010). "Furthermore, MMP2 has been found to be a diagnositc marker for pancreatic carcinoma in pancreatic juice." (PMID 17181856, 2006). "Additionally, RA treatment concealed the MMP2/16 expression in pancreatic cancer cells." (PMID 36247004, 2022). "While, two genes respectively encoding MMP-2 and MMP-9 were simultaneously abnormal up-regulated in pancreatic cancer tissue from diabetic mice of both STZ and db/db, that could act as potential therapeutic targets for significantly suppressing the malignant progression." (PMID 33251135, 2020). "Furthermore, an optimizing therapeutic strategy was further proposed that combining MMP-2/9 inhibitor with gemcitabine significantly enhanced anti-tumor effects on pancreatic cancer under diabetic condition, providing a theoretical basis for clinical applications." (PMID 33251135, 2020). "Previous studies have shown that NUAK1 activates MT1-MMP, which results in promoting the metastasis of breast and pancreatic cancer via activation of MMP-2 and MMP-9, so miR-203-driven invasion of HNSCC cells may be regulated by a pathway that is distinct from EMT induction." (PMID 26882562, 2016). "In addition, pancreatic cancer cells could stimulate the CAFs to produce more MMPs such as MMP-2, MMP-7, MMP-9, and MMP-11 which are used for ECM degradation and are conducive for MICs immigrating through the ECM." (PMID 24587996, 2014). "Therefore, we next examined whether BITC suppresses the secretion of VEGF and MMP-2 from BxPC-3 and PanC-1 pancreatic tumor cells." (PMID 22016776, 2011). "In addition, thrombin stimulates adhesion of pancreatic cancer cells to endothelial cells and extracellular matrix and also stimulates gelatinase matrix metalloproteinase-2 (MMP-2), which is a collagen type IV degrading enzyme, therefore enhancing invasion of the basement membrane." (PMID 24212618, 2011). "The mechanism is that salidroside inhibits the expression of HIF-1α, MMP2, and MMP9 in BxPC-3 cells, making it a potential adjuvant drug for the treatment of pancreatic cancer." (PMID 40563539, 2025). "More in detail, SCs secrete proteins, such as matrix metalloproteinase 2 (MMP-2), cathepsin D, plasminogen activator inhibitor-1 or tansforming growth factor (TGF), thus promoting pancreatic cancer cell aggressive properties, proliferation and invasion." (PMID 40806192, 2025). "Utilizing the CCLE database, it was confirmed that fibroblast cell lines exhibited elevated mRNA levels of the six module genes (GFPT2, MFAP5, CTSK, MMP2, FSTL1, and PRRX1) (accessed on 2 March 2025) compared to pancreatic cancer cell lines." (PMID 40430018, 2025).
pancreatic cancer (continued). "In pancreatic cancer cell lines, PKD2 is known to regulate the secretion of MMP-2, MMP-7 and MMP-9 via a multiprotein complex with ARF1 and ARL1, and Arfaptin2,28,76 aiding the invasion of cells in vitro and in vivo." (PMID 38323010, 2024). "Quercetin treatment (20 μM, 40 μM, 80 μM) was also found to block MMP-2 and MMP-7 expression in pancreatic cancer." (PMID 39335164, 2024). "The increase in E-cadherin expression, along with the inhibition of MMP-2/MMP-9 expression and thus of EMT, was also observed upon α-mangostin treatment in pancreatic cancer cell lines MIAPaCa-3 and BxPCa-2." (PMID 38540096, 2024). "Two interesting matrix remodeling genes are MMP2 and CXCR4, which are involved in promoting cell motility and invasion in pancreatic cancer." (PMID 36765586, 2023). "Migration and invasion of gastric, and pancreas cancers were enhanced through the overexpression of RRM2 accompanied by raised MMP2 and MMP-9 levels, and activation of NF-KB and AKT signaling." (PMID 37529110, 2023). "The polyphenol curcumin has been shown to inhibit cell migration and decrease MMP-2 and MMP-9 expression following H2O2 exposure in pancreatic cancer cells, as well as reducing MMP-2 levels in colon cancer cells." (PMID 36674555, 2023). "Studies have shown that after the ISO treatment of pancreatic cancer cells, the expression levels of VEGF, MMP2, and MMP9 decreased, but the expression level of E–cadherin increased." (PMID 36558992, 2022). "Different from previous studies, this study demonstrated for the first time that miR-490-5p mimic attenuated the levels of MMP2, MMP9, and N-cadherin and enhanced E-cadherin level in pancreatic cancer cells, which was reversed by MAGI2-AS3 overexpression." (PMID 35043728, 2022). "To examine the underlying mechanism by which COL11A1 promotes the invasion and migration of pancreatic cancer cells, we measured the expression levels of EMT markers and MMP-2/9 using Western blotting and immunofluorescence." (PMID 35327583, 2022). "Recent reports have shown that FOXM1 contributes to pancreatic cancer invasion and progression by increasing the expression of MMP-9, MMP-2 and VEGF and downregulated FOXM1 expression results in the inhibition of pancreatic cancer cell growth and invasion." (PMID 33867818, 2021). "Knockdown of NR5A2 in pancreatic cancer decreased the expression of FGB, TWIST, SNAIL, MMP9, MMP3, MMP2, and Vimentin, as well as increased the expression of the epithelial markers β-catenin and E-cadherin." (PMID 34277436, 2021). "A previous study reported that MMP2 and MMP9 were mainly secreted by pancreatic cancer cells to modulate the neural cancerous microenvironment." (PMID 32064233, 2020). "This gene is highly expressed in pancreatic cancer cells and stimulates metastasis by upregulating Discoidin Domain Receptor Tyrosine Kinase 1 (DDR1), Matrix Metallopeptidase 2 (MMP2) and Matrix Metallopeptidase 9 (MMP9)." (PMID 32000679, 2020). "Rg3 effectively inhibits the formation of pancreatic cancer vasculogenic mimicry by downregulating the expression of VE-cadherin, EphA2, MMP9, and MMP2." (PMID 32733585, 2020). "When STZ and db/db mice bearing pancreatic cancer were treated with a selective inhibitor of MMP-2 and MMP-9, SB-3CT, for 20 days in this study, the expressions of MMP-2 and MMP-9 significantly decreased (all p<0.05)." (PMID 33251135, 2020). "Among these genes, our study further proved that the expression of both MMP-2 and MMP-9 was abnormally upregulated in pancreatic cancer tissue under diabetic conditions." (PMID 33251135, 2020). "STAT3 leads to the expression of NGF, MMP2, and MMP9 in pancreatic cancer cells so that they can migrate and invade." (PMID 32555170, 2020). "Luteolin treatment in a dose-dependent manner inhibited EMT, protein expression of MMPs (i.e., MMP2/7/9), and STAT3 signaling, as well as decreased the invasiveness of pancreatic cancer cells." (PMID 32717779, 2020).
pancreatic cancer (continued). "Interfering of YTHDF2 upregulates the expression of MMP2 and MMP9 that possess the capability to promote cell adhesion, thus enhancing the invasion and adhesion of pancreatic cancer cells." (PMID 31959747, 2020). "Natural compounds, including silibinin and oxymatrine, have inhibitory effect on MMP-2 and MMP-9 via p38 inactivation in gastric and pancreatic cancer cells." (PMID 32349276, 2020). "TGF-β1 stimulates MMP-2 expression through the activation of the Rac1/ROS/NFκB pathway and thus increases invasiveness of SW1990 human pancreatic cancer cells." (PMID 31980722, 2020). "For instance, NFATc1 induced malignant growth phenotype in pancreatic cancer cells by upregulating MYC and promoted metastasis of mammalian cancer cells via MMP-2 upregulation." (PMID 31040921, 2019). "In pancreatic cancer, NDRG1 acts as an anti-tumor factor by repressing proliferation and impeding invasion and migration of the proteins p-STAT3, PI3K, p-AKT, MMP2, MMP9." (PMID 31205821, 2019). "Apart from ECM components, we found also that hMENA11a-transfected cells showed a reduced secretion of ECM remodeling enzymes, such as matrix metalloproteinase 2 (MMP2), in agreement with our recent observation in pancreatic cancer cell lines." (PMID 29907768, 2018). "Hypoxia plays a critical role in pancreatic cancer progression by inducing HIF1 to activate numerous genes involved in invasion and metastasis, such as NF-κB, MMP-2, quiescin-sulfhydryl-oxidase-1 (QSOX1), CX3CR1, and lysyl-oxidase (LOX)." (PMID 30060755, 2018). "Collectively, our study provides a novel regulatory pathway involving TM4SF1, DDR1, MMP2 and MMP9, which promotes the formation and function of invadopodia to support cell migration and invasion in pancreatic cancer." (PMID 28368050, 2017). "negative HIC1 expression predicted poor dignosis; inhibited the invasion and metastasis of pancreatic cancer cells both in vitro and in vivo; repressed the expression of STAT3 target genes, including c-Myc, VEGF, CyclinD1, MMP2 and MMP9." (PMID 29254283, 2017). "Overexpressed miR-221/222 can contribute to the expression of matrix metalloproteinases-2 (MMP-2) and MMP-9 by directly targeting tissue inhibitor of MMP-2 (TIMP-2), thereby facilitating pancreatic cancer invasion." (PMID 28261196, 2017). "MMP2, MMP9 are two important MMPs that play a vital role in pancreas development got differentially methylated in pancreatic cancer." (PMID 28423671, 2017). "A similar inhibition of the upregulation of MMP-2 and MMP-9 by PRO has also been reported in nasopharyngeal carcinoma, pancreatic cancer, gastric adenocarcinoma, melanoma, prostate cancer and of MMP-9 in medulloblastoma and infantile hemangioma." (PMID 27899953, 2016). "Our work demonstrates that LXA4 attenuates cell invasion in pancreatic cancer by suppression of the ROS/ERK pathway and consequent MMP-9/MMP-2 transcription not only in a pancreatic cancer cell line but also in a CoCl2-induced model of hypoxia." (PMID 26649143, 2016). "In vitro, we demonstrated that overexpression of Nodal promotes pancreatic cancer cell migration and invasion, induces EMT and enhances the expression of MMP2 and CXCR4." (PMID 25557170, 2015). "Matrix metalloproteinase 2 (MMP-2) promotes the invasion of a variety of cancer cells, including pancreatic cancer cells." (PMID 26213494, 2015). "Mechanistic investigation revealed that Nodal induced an aggressive phenotype in pancreatic cancer cells by initiating an EMT process and increasing MMP2 secretion." (PMID 25557170, 2015). "In our previous study, we found that SDF-1α/CXCR4 upregulated MMP-2 expression and induced the invasion of PANC1 and SW-1990 pancreatic cancer cells by activating p38 MAPK." (PMID 26213494, 2015). "Because MMP-2 and MMP-9 are important factors that influence cell invasion, we showed that pancreatic cancer cell invasion is dependent on miR-221/222 regulation." (PMID 25883224, 2015).
pancreatic cancer (continued). "The expression of the matrix metalloproteinases (MMPs) MMP-2 and MMP-9 was increased in miR-221/222 mimic-transfected pancreatic cancer cells." (PMID 25883224, 2015). "This study provides further insight into the molecular mechanism of GSK3β-induced pancreatic cancer invasion, and will allow exploration of novel therapeutic strategies for pancreatic cancer that target GSK3β and/or CXCR4/MMP-2." (PMID 26213494, 2015). "The focus of this study was to determine the effects of GSK3β and investigate its molecular mechanism of action, specifically via the GSK3β-CXCR4/MMP-2 pathway, in PANC1 pancreatic cancer cells." (PMID 26213494, 2015). "MMP-2 and MMP-9 are crucial in ECM degradation and are essential for the invasion and metastasis of pancreatic cancer." (PMID 24932309, 2014). "Western blots of xenograft tissues suggested that chronic nicotine induced while GABA inhibited MMP-9, MMP-2 and EGR-1 in pancreatic cancer." (PMID 25260978, 2014). "MMP1, MMP2 and MMP9, as well as their inhibitors, TIMP1 and TIMP2, were detected in pancreatic cancers, and their concentrations correlated with tumor grade, tumor size, invasive characteristics, and metastasis." (PMID 23744510, 2013). "The mean concentration of MMP-2 and MMP-9 in blood of pancreatic cancer patients is significantly higher than in the control group." (PMID 23768069, 2013). "Previously, α-mangostin has been shown to suppress the phosphorylation of ERK, leading to the inhibition of MMP-2 and MMP-9 in pancreatic cancer cells." (PMID 23833675, 2013). "Here, for the first time, we found that emodin inhibited the angiogenesis of pancreatic cancer in vivo, downregulated the expression of NF-κB and NF-κB-regulated proteins with roles in angiogenesis inhibition (VEGF, MMP-2, MMP-9, and eNOS)." (PMID 22876305, 2012). "MMP1, MMP2, MMP7, and MMP9 have also been shown to be expressed in pancreatic tumor, but the effect of cysteamine on protein and mRNA levels for all these MMPs was not examined except for MMP9." (PMID 22532830, 2012). "Taken together, our data provides convincing evidence that BITC inhibits pancreatic tumor angiogenesis by targeting STAT-3 and inhibiting HIF-1α/VEGF/MMP-2/Rho-GTPases." (PMID 22016776, 2011). "We provide evidence that BITC dose-dependently inhibits the migration, invasion, and neovascularization of human pancreatic cancer and endothelial cells by targeting HIF1α, VEGF, MMP-2, and Rho-GTPases through the STAT-3 dependent pathway." (PMID 22016776, 2011). "At present, many serum markers for pancreatic cancer have been reported; including CEA, PNA-binding glycoproteins, hTert(telomerase catalytic subunit) and matrix metalloproteinase-2(MMP-2)." (PMID 20587030, 2010). "MMP-2 staining was found primarily in PSC adjacent to cancer cells and secretion of MMP-2 by PSC by far exceeds that of cancer cells, although pancreas carcinoma cells express some MMP-2." (PMID 24281180, 2010). "MMP-2 contributes to cancer-nerve crosstalk in breast, prostate, and pancreatic cancers, whereas neural cell secretion of CCL2 is a contributor to cervical, prostate, and pancreatic cancer PNI." (PMID 40160208, 2025). "Immunohistochemistry showed that the HIF-1α/MMP2 and HIF-1α/MMP9 signaling pathways in the tumor model were blocked, proving the role of the HIF-1α/MMPs signaling pathway in the occurrence and development of pancreatic cancer." (PMID 40563539, 2025). "α-mangostin (>7.5 μM) was found to inhibit MMP-2 and MMP-9 in pancreatic cancer cells." (PMID 38540096, 2024). "In addition, 5 μM genistein inhibited MMP-2 and MMP-9 expression in Mia-PaCa2 pancreatic cancer cells, as assessed by Western blotting, in a time-dependent manner." (PMID 39335164, 2024). "The MMP-2, -9, and -14 selective inhibitor MMI-166 was a little toxic to cells derived from human cervical adenocarcinoma (designated CAC-1 cells) and the hamster pancreatic cancer cell line PGHAM-1." (PMID 38003553, 2023).
pancreatic cancer (continued). "Furthermore, noradrenaline can increase MMP-2, MMP-9, and VEGF synthesis and the metastatic potential of pancreatic cancer cells." (PMID 36213817, 2022). "To further verify that COL11A1 promoted the EMT process in pancreatic cancer cells by activating the AKT/GSK-3β/Snail signaling pathway, we first detected the expression levels of E-cad, N-cad, VIM, and MMP-2/9 in PANC-1 cells with different treatments by Western blotting." (PMID 35327583, 2022). "MMP-2 wasfound to be highly expressed in these cells, and also there was a correlationbetween the presence of CTM and DVT, which opens perspectives in the monitoring ofpatients with pancreatic cancer, so prone to DVT." (PMID 35107490, 2022). "Similarly, other pancreatic cancer cells such as DanG, HPAF-II, L3.6, and BxPC3 cells all express various levels of both MMP2 and MT1-MMP." (PMID 33740019, 2021). "Studies have shown that MMP-1, MMP-2, MMP-7, MMP-9, membrane type 1-MMP (MT1-MMP), MT2-MMP, and MT3-MMP are overexpressed in pancreatic cancer tumors, while MMP-2, MMP-7, and MMP-9 have been identified as potential biomarkers of pancreatic cancer." (PMID 34809634, 2021). "Several of these MMPs are upregulated in pancreatic cancer, particularly MT1-MMP, MMP2 and MMP9." (PMID 33740019, 2021). "Indeed, knockdown of MMP2 blunted the matrix degradation induced by overexpression of MT1-MMP, supportive of cross-talk between these two pro-invasive proteinases in pancreatic tumor cells." (PMID 33740019, 2021). "TSPAN1 could up-regulate matrix metalloproteinase 2 (MMP2) through PLCγ to promote migration and invasion of pancreatic cancer cells." (PMID 34852709, 2021). "Intriguingly, HIF-1α could also mediate stress-induced pancreatic tumor growth and angiogenesis via regulating the expression of VEGF, matrix metalloproteinase 2 (MMP-2) and matrix metalloproteinase 9 (MMP-9)." (PMID 32587480, 2020). "Contrasted to that in pancreatic cancer cells, the expression of Mmp2 did not change, and Mmp9 was downregulated by Ythdf2-KO in spermatogonia." (PMID 31959747, 2020). "To better understand the molecules involved in PRMT5 signalling‐induced pancreatic cancer cells invasion, we identified whether PRMT5 affected MMP2 and MMP9 expression in pancreatic cancer cells." (PMID 31851779, 2020). "Furthermore, HOP knockdown downregulates matrix metalloproteinase-2 (MMP-2), resulting in reduced invasion of pancreatic cancer cells." (PMID 32121660, 2020). "Additionally, to better understand and compare the therapeutic effect of targeting MMP-2 and MMP-9 with SB-3CT, a standard chemotherapy for pancreatic cancer, i.e., gemcitabine, was used." (PMID 33251135, 2020). "However, the mechanism of abnormally upregulated MMP-2 and MMP-9 expression in pancreatic cancer from diabetic STZ and db/db mice was unclear." (PMID 33251135, 2020). "Our further results indicated that GnRH can regulate the expression level of MMP2 but not MMP9 in pancreatic cancer cells." (PMID 31263453, 2019). "Moreover, the roles of MMP-2 and MMP-9 in metastasis in pancreatic cancer are also demonstrated by a positive correlation between the expression of these two MMPs and the microvessel density, suggesting their involvement in the angiogenic processes." (PMID 30301152, 2018). "Additionally, down-regulation of the PI3K/Akt pathway was demonstrated to be involved in α-mangostin-reduced viability, EMT, MMP-2/MMP-9 expression, and invasion in BxPc-3 and Panc-1 pancreatic cancer cells." (PMID 28537893, 2017). "Co-expression of MMP9, MMP2 and TNC contributes to pancreatic cancer progression." (PMID 29088796, 2017). "The data show that highly expressed miR-221/222 could inhibit TIMP-2 and further upregulate the expression of MMP-2 and MMP-9, which would promote the invasion of pancreatic cancer cells." (PMID 25883224, 2015).